CRP (C-reactive protein)
Diseases named in the same sentence as CRP in open-access papers (continued):
Sharing a sentence is not in itself a finding about the gene and the disease.
systemic lupus erythematosus (continued). "However, several studies have indicated similar alterations in ESR and CRP levels in various other diseases including systemic lupus erythematosus and other systemic infections." (PMID 38383594, 2024). "Interestingly, FLCs correlate with CRP, Systemic Lupus Erythematosus Diseases Activity Index (SLEDAI) and Visual analogue scale VAS scores." (PMID 37298479, 2023). "However, some lupus patients present with a proinflammatory phenotype, with elevated serum CRP and higher frequencies of pleuritis and myositis." (PMID 36319843, 2022). "SLE (systemic lupus erythematosus) is known to cause a low WBC, high ESR and a low CRP level." (PMID 36527007, 2022). "Furthermore, emerging data indicate that CRP constitutes an autoantigen in systemic lupus erythematosus." (PMID 34945133, 2021). "This review describes CRP-mediated biological effects and the regulation of CRP release in relation to aspects of cardiovascular disease and mechanisms of autoimmunity, with particular focus on systemic lupus erythematosus." (PMID 34945133, 2021). "Although several previous reports have described that CRP could be a biomarker in the patients with systemic lupus erythematosus or AAV with renal involvements, CRP levels may be related to organ involvements other than the kidney in the patients with AAV." (PMID 33664381, 2021). "A review by Baicus C concluded that the ratio of ESR/CRP >15 suggests lupus flares, while a ratio of less than 2 may indicate the occurrence of bacterial infections." (PMID 33732661, 2021). "Considering the protective effects of CRP seen in animal models of lupus, it is tempting to speculate that CRP acts as a modulator of IFN-α production by altering the immune complex handling by plasma-cytoid dendritic cells." (PMID 34945133, 2021). "Indeed, protective effects of CRP in the disease process have been demonstrated in animal models of lupus." (PMID 33584722, 2020). "Beyond that, there are many other types of diagnostic indicators in lupus, including acute-phase proteins, erythrocyte sedimentation rate (ESR), C-reactive protein (CRP), and complement protein level, but little is known about the stability and accuracy of them." (PMID 28785369, 2017). "However, circulating PGRN levels correlated with disease severity, which has been previously documented also in patients with systemic lupus erythematosus or with CRP levels in obese and type 2 diabetic patients." (PMID 26339140, 2015). "Anti-CRP-Ab levels were studied in relation to routine laboratory tests, urine analysis, levels of C3, C4, other immunological markers and the overall disease activity as assessed by Systemic Lupus Erythematosus Disease Activity Index (SLEDAI)." (PMID 26704903, 2015). "However, as known, low CRP levels can also be seen in diseases with marked tissue inflammation such as systemic lupus erythematosus." (PMID 21331754, 2011). "However, there is evidence that CRP levels rise modestly despite active tissue-damaging inflammatory processes in some disorders, including systemic lupus erythematosus, scleroderma, dermatomyositis, Sjögren’s syndrome, ulcerative colitis, graft-versus-host disease and leukemia." (PMID 41429071, 2025). "The possible role of CRP in other autoimmune conditions related to RA, such as systemic lupus erythematosus (SLE), has also been investigated." (PMID 40943152, 2025). "CRP gene polymorphism influences gene expression and may predispose to systemic lupus erythematosus, but do not appear to be associated with increased risk for cardiovascular diseases." (PMID 37564640, 2023). "CRP levels are elevated in systemic lupus erythematosus (SLE) if there is the presence of serositis or synovitis." (PMID 36381804, 2022). "Patients with systemic lupus erythematosus (SLE) often display modest elevations of CRP despite raised disease activity and increased (IL-6)." (PMID 34680097, 2021).
systemic lupus erythematosus (continued). "CRP evaluation is used to exclude the development of infectious complications in systemic lupus erythematosus (SLE)." (PMID 33266394, 2020). "In systemic lupus erythematosus (SLE), a multiorganic inflammatory disorder, CRP levels can be very low despite inflammatory activity." (PMID 31760445, 2019). "Childhood-onset systemic lupus erythematosus (c-SLE) is a chronic autoimmune disease which increases cardiovascular risk factors (CRF) such as elevated homocysteine, TNF-α, and hs-C reactive protein." (PMID 29316941, 2018). "Additionally, in an open-label trial of patients with psoriatic arthritis, pioglitazone reduced both tender and swollen joint counts, and pioglitazone decreased CRP and serum amyloid A and improved insulin sensitivity in patients with uncomplicated systemic lupus erythematosus." (PMID 24020899, 2013). "Furthermore, in two murine lupus models, subcutaneous CRP injections delayed the disease onset, reversed nephritis, and prolonged the survival of the animals - indicating a preventive and disease-modifying role for CRP in SLE." (PMID 20003354, 2009). "Disease activity parameters included Systemic Lupus Erythematosus Disease Activity Index 2000 (SLEDAI-2K) score, erythrocyte sedimentation rate, C-reactive protein level, anti-double strain DNA antibody level, complement fractions C3 and C4 levels." (PMID 38562920, 2024). "Genetically predicted smoking initiation (OR = 1.167, 95%CI 1.005–1.355, P = 0.043), systemic lupus erythematosus (SLE) (OR = 1.086, 95%CI 1.017–1.160, P = 0.014) and higher CRP (OR = 1.199, 95%CI 1.019–1.410, P = 0.028) were suggestively associated with an increased risk of PBC." (PMID 38704596, 2024). "The results also showed that TGP contributed to a betterment in improving other outcomes related to lupus activity, such as ESR, CRP, complement proteins (C3, C4), and immunoglobulins (IgA, IgM)." (PMID 35173622, 2022). "Concerning human diseases, the role of CRP was even more complex and ambiguous: On the one hand, in autoimmune conditions like Systemic Lupus Erythematosus (SLE), increased CRP levels contributed to efficient clearance of potential autoantigens." (PMID 35402541, 2022). "Only a few studies have reported methods for effective distinction between bacterial infections and lupus flares in SLE in the past, and they have only explored the indicators, including WBC, CRP, PCT, and nCD64, independently." (PMID 33732661, 2021). "For routine examination indicators, the levels of WBC, NEUT, ESR, CRP, and PCT in the bacteria-infected group were significantly elevated compared to those in the lupus flares group." (PMID 33732661, 2021). "These qualities enable CRP to contribute to efficient clearance of cell remnants and immune complexes by complement activation/modulation, opsonization, and phagocytosis, biological processes considered dysfunctional in systemic lupus erythematosus (SLE)." (PMID 33584722, 2020). "It means that CRP and MDA values with organ involvement in lupus patients in this study had a very low or weak correlation." (PMID 32695177, 2020). "Increased level of C-reactive protein (CRP) was related to several disease conditions consisting of being obese, experiencing heart problems, as well as lupus." (PMID 32175075, 2020). "Serum IFN-λ1 levels were positively correlated with Systemic Lupus Erythematosus Disease Activity Index (SLEDAI), anti-dsDNA antibody, C-reactive protein (CRP) and negatively correlated with complement." (PMID 21679442, 2011). "C-reactive protein also exhibits a distinct anti-inflammatory activity indicated by its protective effects against endotoxic shock, allergic encephalitis, inflammatory alveolitis, nephrotoxic nephritis, and systemic lupus erythematosus (SLE)." (PMID 19690638, 2007). "High levels of C‐reactive protein (CRP) in systemic lupus erythematosus are not usually a sign of disease activity but more of a severe bacterial infection." (PMID 41591508, 2026).
systemic lupus erythematosus (continued). "Additionally, inflammatory diseases, including myocarditis and systemic lupus erythematosus (SLE), contribute to myocardial fibrosis through persistent immune activation and fibroblast stimulation, with elevated troponins and CRP indicating myocardial damage and systemic inflammation." (PMID 40291288, 2025). "An ESR/CRP ratio of 2.0–2.4 may favor autoimmune flare over infection, and a higher ESR/CRP ratio has been correlated with immune-mediated inflammation in systemic lupus erythematosus." (PMID 40725261, 2025). "SLE: systemic lupus erythematosus; ESR: erythrocyte sedimentation rate; CRP: C-reactive protein." (PMID 39866998, 2024). "A 75-year-old woman with a history of systemic lupus erythematosus (SLE) presented with isolate ocular symptoms, including a left scleral hematoma, elevated erythrocyte sedimentation rate (ESR), and C-reactive protein (CRP)." (PMID 39886706, 2024). "Additionally, antibodies against C-reactive protein (CRP) have been detected in patients with active LN, and their levels were found to be correlated with the Systemic Lupus Erythematosus Disease Activity Index (SLEDAI) score (p = 0.002)." (PMID 38255879, 2024). "Previous studies have suggested that positive RF frequently coexists with elevated concentration of inflammatory markers, such as CRP, procalcitonin (PCT) and interleukin-6 (IL-6) in patients with Sjogren’s syndrome, systemic lupus erythematosus, RA and viral hepatitis." (PMID 34543280, 2021). "Unlike GlycA levels, the CRP concentrations of non-lupus nephritic controls were not significantly different from those of patients with active SLE." (PMID 32012794, 2020). "In patients with lupus, AGP and CRP increase whereas transferrin decreases." (PMID 31766160, 2019). "Anti-CRP and -SAP aAbs have been reported in patients with systemic lupus erythematosus." (PMID 26797217, 2016). "Many patients with active systemic lupus erythematosus do not have high plasma concentrations of CRP but do have marked increases during bacterial infection." (PMID 24346772, 2014). "In analogy to complement deficiency genetic lack of CRP or SAP is associated with impaired clearance of apoptotic cells and the onset of lupus." (PMID 21637713, 2011). "It has been reported that a single dose of human C-reactive protein (CRP) can prevent and reverse the renal damage in murine models of spontaneous lupus, as well as the rapid-onset immune complex disease induced in the accelerated nephrotoxic nephritis (ANTN) model." (PMID 20039408, 2010). "Notably, some studies have observed attenuated renal-specific indicators (e.g., proteinuria and hematuria) and improved systemic inflammatory markers (C-reactive protein, erythrocyte sedimentation rate) in ESRD patients, suggesting partial control of lupus activity." (PMID 41561941, 2025). "Interestingly, endothelial activation, also associated with serum markers of the inflammatory process of SLE (low C4; increased CRP or IL-6), appears not to be associated with the SLE activity index (Systemic Lupus Erythematosus Disease Activity Index [SLEDAI])." (PMID 36622519, 2023). "Given the essential biological functions of pentraxins, such as CRP, in facilitating silent removal of cellular debris via Fc-receptors and by interacting with the complement system it is perhaps not surprising that administration of CRP to a murine lupus model prevent and reverse ongoing nephritis." (PMID 33584722, 2020). "The sIL-2R level was correlated with the AST, ALT, CRP, T-bil, Alb, and PT-INR levels, suggesting that the sIL-2R level reflects the extent of CMV hepatitis activity in infected patients, as in those with systemic lupus erythematosus and sarcoidosis, both of which feature T-cell activation." (PMID 32908853, 2020). "Two new studies had also determined that RDW was increased in patients with systemic lupus erythematosus (SLE) and related with SLE disease activity index (SLEDAI), ESR, and CRP." (PMID 30174952, 2018).
systemic lupus erythematosus (continued). "Interestingly, anti-CRP-Ab recognize the mCRP subunits, but not the native pentameric form of CRP, and thus—as other lupus autoantibodies—can be considered neo-epitope specific." (PMID 26704903, 2015). "The expression of human C-reactive protein (P03/P04) in the lupus-prone NZB/NZW F1 mice has delayed the initiation of glomerulonephritis and death, suggesting that high level of C-reactive protein may present a self-protective process against glomerulonephritis." (PMID 23762862, 2013). "In contrast, in PBMCs, lower expression of lncRNA ITSN1-2 compared to healthy individuals and systemic lupus erythematosus (SLE) patients, with a negative correlation to CRP levels." (PMID 40629453, 2025). "Our completely negative observations do not confirm that human CRP has reproducible antiinflammatory or immunomodulatory effects in these murine models, nor do they support the suggestion that CRP might be useful for therapy of lupus or immune complex–mediated nephritis." (PMID 20039408, 2010). "An exception to this is in systemic lupus erythematosus (SLE), where CRP does not typically rise in acute flare but does in concurrent infections rendering it a useful biomarker for infection." (PMID 30225546, 2018). "CRP increases significantly in SLE patients with concomitant infection, but increases only slightly or not at all in patients with a lupus flare." (PMID 29581911, 2018).
ankylosing spondylitis (180 papers, 2009 to 2026). An autoimmune chronic inflammatory disorder characterized by inflammation in the vertebral joints of the spine and sacroiliac joints. "An increased Bath Ankylosing Spondylitis Disease Activity Index was found to be associated with a reduced TNFi retention whereas an elevated CRP was associated with a prolonged retention." (PMID 40063233, 2025). "Prevotella_2 was a minor genus in Prevotellaceae, associated with cardiovascular risk, ankylosing spondylitis and increased levels of C-reactive protein." (PMID 35356519, 2022). "Prevotella 2 is a genus of Gram-negative, anaerobic bacteria that exists in the gut and are relevant to multiple disease states, including an increased lifetime risk of cardiovascular disease, ankylosing spondylitis, and increased levels of C-reactive protein." (PMID 33384967, 2020). "Certain polymorphisms of the gene encoding IL-38 have been found to be associated with RA, PsA, and ankylosing spondylitis, but also with cardiovascular diseases and C-reactive protein (CRP) levels, implying a broader inhibitory role of this molecule." (PMID 30871134, 2019). "A hospitalized-based cohort study suggested that elevated C-reactive protein (CRP) levels are associated with radiographic sacroiliitis progression in ankylosing spondylitis (AS) patients." (PMID 30768617, 2019). "It has been shown that MMP-degraded CRP provides a more discriminative diagnostic potential compared to that of full-length CRP in ankylosing spondylitis (AS) patients." (PMID 27039382, 2016). "This has been shown in other diseases such as in patients with ankylosing spondylitis, where the degradation markers of CRP, the CRP-MMP and CRP-Cat, had a higher diagnostic value than the total CRP." (PMID 23805173, 2013). "Notably, indicators of systemic inflammation such as uveitis or elevated CRP levels have been linked to increased CVD in ankylosing spondylitis patients." (PMID 38319376, 2024). "Furthermore, it has been reported that in individuals with ankylosing spondylitis, high levels of serum CRP were associated with a greater number of enlarged corneal DCs, when compared to healthy controls." (PMID 33362451, 2020). "In conclusion, we demonstrated that elevated TNC levels were correlated with persistent activity assessed by BASDAI and CRP levels in ankylosing spondylitis." (PMID 40564778, 2025). "To follow up on this primary finding, we employed M-learner to examine two secondary outcomes for ankylosing spondylitis, i.e., C-reactive protein (CRP) and erythrocyte sedimentation rate (ESR)." (PMID 41282753, 2025). "One study reported that serum levels of TUG1 were negatively correlated with CRP in ankylosing spondylitis patients." (PMID 39539543, 2024). "Despite five months of infliximab therapy, the patient’s symptoms persisted, with a Bath Ankylosing Spondylitis Disease Activity Index of 4 and an Ankylosing Spondylitis Disease Activity Score with CRP of 3.8, along with elevated CRP levels (37.4 mg/L)." (PMID 39258044, 2024). "In studies used to diagnose ankylosing spondylitis (AS), specific markers such as human leukocyte antigen B27 (HLA-B27) and C-reactive protein (CRP) are positive in 85-95% of AS patients." (PMID 38162641, 2023). "(i) Some ankylosing spondylitis patients have active disease despite normal C-reactive protein and erythrocyte sedimentation rate levels." (PMID 35685583, 2022). "Secondary outcomes included the assessment of disease activity, tender entheses, spinal mobility, serum C-reactive protein (CRP), the Bath Ankylosing Spondylitis Disease Activity and Functional Index, and the Childhood Health Assessment Questionnaire (CHAQ)." (PMID 35941676, 2022). "The Ankylosing Spondylitis Disease Activity Score (ASDAS) computes the values of acute-phase reactants C-reactive protein (CRP) and erythrocyte sedimentation rate (ESR) in addition to the patient-reported outcomes." (PMID 35652077, 2022).